RNU2-16P (RNA, U2 small nuclear 16, pseudogene)
Gene: Small nuclear RNA gene on chromosome 4 (75,829,454 to 75,829,589, reverse strand). Ensembl gene ENSG00000222644.
Homologues: Orthologues: rat LOC120099539 (44% identical), rabbit U2 (34% identical). Paralogues in human: RNU2-14P (62% identical), RNU2-54P (54% identical), RNU2-22P (53% identical), RNU2-41P (53% identical), RNU2-72P (52% identical), RNU2-24P (48% identical), RNU2-55P (47% identical), RNU2-10P (46% identical), RNU2-53P (46% identical), U2 (46% identical), RNU2-12P (45% identical), RNU2-42P (45% identical), and 64 more.